FSCN1 (fascin actin-bundling protein 1)
Diseases named in the same sentence as FSCN1 in open-access papers (continued):
Sharing a sentence is not in itself a finding about the gene and the disease.
cancer (continued). "Understanding these roles and mechanistic regulation of FSCN1 in cancers will be crucial for the development of therapeutic interventions targeting FSCN1." (PMID 33614909, 2021). "Downregulation of FSCN1, in a variety of cancer cell lines, not only inhibited their proliferative capacity but also their migratory and invasive abilities." (PMID 33614909, 2021). "In summary, we show that the high expression of FSCN1 indicates poor prognosis and radiotherapy response of cancer patients with PIK3CA alterations." (PMID 34249689, 2021). "MiR-145 negatively regulates FSCN1 mRNA levels in many different human cancers, including nasopharyngeal, laryngeal, esophageal, breast, lung, stomach, liver, colon, bladder, cervix, prostate, and cartilage cancers." (PMID 33614909, 2021). "Investigation of the relationship among mitochondrial metabolism, FSCN1, and metastatic colonization in cancers has begun;65 more widespread investigations can be expected in the next few years." (PMID 33614909, 2021). "Functional studies using human cancer cell lines have shown that FSCN1 is involved in the regulation of cancer-related cellular properties, such as growth, migration, invasion, metastasis, and therapeutic resistance." (PMID 33614909, 2021). "Although FSCN1 is a promising biomarker candidate for aggressive carcinomas, its current LOE is low (level IV or V)." (PMID 33614909, 2021). "Over the last 5 years, fascin-1 (FSCN1), a globular actin-binding protein, has emerged as an interesting novel biomarker for the most aggressive human carcinomas." (PMID 34248854, 2021). "The absence or low expression of FSCN1 in normal epithelia is altered in different human carcinomas." (PMID 33614909, 2021). "Strong positive expression of LINC00152 and FSCN1 proteins were identified in the cytoplasm of cancer tissues, meanwhile, weak staining was observed in normal tissues." (PMID 32042551, 2020). "Previously, researchers had analyzed FSCN1 expression in cancers, such as esophageal, gastric, and oral carcinoma." (PMID 31043585, 2019). "In previous studies, researchers have analyzed FSCN1 expression in cancers, such as esophageal, gastric, and oral carcinoma." (PMID 31043585, 2019). "In the immunohistochemical analyses, FSCN1 expression was increased in all of the TSCC tissues (95/95) in comparison with the matched adjacent non-carcinoma tissues." (PMID 31043585, 2019). "Similar studies investigating miR-145 on FSCN1 expression in several cancer cell lines (gastric, colorectal, non-small cell lung) have shown significant inhibition in cancer cell phenotypes including metastasis, invasion and proliferation." (PMID 28596604, 2017). "According to Kaplan-Meier plotter, we found that a higher FSCN1 expression was negatively correlated with overall and progression-free survival rates of all cancer patients, even stratified by aggressive parameters (p<0.05)." (PMID 29285273, 2017). "T4 or poorly- differentiated cancer patients with high FSCN1 expression showed a low progression-free survival time than those with its low expression (p<0.05)." (PMID 29285273, 2017). "Upregulation of FSCN1 has been indicated in various cancer cell types such as stomach, colon, lung, ovary and breast." (PMID 29162880, 2017). "In recent years, Fscn1 has gained significant attention due to its upregulation in aggressive human carcinomas." (PMID 25607881, 2015). "Fascin1 (FSCN1) involved in cell motility and filopodia assembly plays important roles in biological processes such as cancer invasion and metastasis of multiple epithelial tumors." (PMID 24378809, 2014). "FSCN1 plays important roles in cell migration, motility, adhesion and cellular interactions and act as an oncogene in multiple types of cancer by increasing cell motility." (PMID 25433493, 2014). "Several cancer-related transcripts were found to be up-regulated as well, including the mRNA for actin-bundling protein Fscn-1." (PMID 20657781, 2010).
cancer (continued). "Similar to CREB, AhR functions in the context of transcriptional coactivators or corepressors: it will be of future interest to identify the upstream signaling mechanisms by which CREB and AhR binding to the FSCN1 promoter are activated in carcinoma cells." (PMID 19340314, 2009). "FSCN1 is upregulated in multiple cancers and is related to cancer metastasis and a poor prognosis." (PMID 37491232, 2023). "FSCN1 participates in the tumorigenesis process of a variety of cancers." (PMID 37491232, 2023). "However, aberrantly high expression of FSCN1 in the majority of cancers has made it a growing focus of attention in the cancer field, with a dramatic rise in research publications over the last decade." (PMID 37596693, 2023). "Based on the anti-angiogenic potency of FSCN1 knockdown observed in our data, we anticipate that NP-G2-044 may function not only as an anti-metastatic drug for malignant tumors but also as a promising drug for pathological ocular neovascularization." (PMID 37596693, 2023). "Since FSCN1 overexpression has been correlated with poor clinical outcomes and shorter survival across different cancer types, FSCN1 has been suggested as a therapeutic target for blocking migration, invasion and metastasis, encouraging FSCN1 inhibitors identification." (PMID 37875732, 2023). "Evidence has shown that miR-200b could target fascin actin-bundling protein 1 (FSCN1), and p70S6K1 and these two target genes (FSCN1 and p70S6K1) are involved in the chemoresistance of cancers." (PMID 36276139, 2022). "FSCN1 was found to be overexpressed in squamous cell carcinoma of the cervix and might be involved in the metastasis of cancers induced by some types of HPV, hypothetically through attenuation of intercellular adhesion and induction of cell motility." (PMID 35178306, 2022). "Moreover, studies have demonstrated that FSCN1 also promoted EMT in cancers including HCC, and as predictable its suppression significantly suppressed vimentin expression, a key marker of EMT." (PMID 35081125, 2022). "FSCN1 is differentially expressed in cancer cells, where it organizes actin filaments into pseudopodia and enhances ECM degradation by matrix metalloprotease (MMPs) and, therefore, contributes to the malignant phenotype and development and progression of tumors." (PMID 36591473, 2022). "FSCN1 is also positively correlated with increased migration and invasion of cancer cells." (PMID 35711849, 2022). "FSCN1 is an important mediator of carcinoma invasion and metastasis." (PMID 35178306, 2022). "Then, we found that expression of the FSCN1 gene was up-regulated in a variety of cancers compared with adjacent tissues, which suggested that the FSCN1 gene may be an oncogene." (PMID 34249689, 2021). "Notably, previous studies revealed that IGF2BP1, acted as a m6A reader, played an oncogenic role in cancer cells, through stabilizing methylated mRNAs of oncogenic proteins, including FSCN1, TK1, MARCKSL1, and MYC." (PMID 33853613, 2021). "Fascin-1 (FSCN1) is an actin-bundling protein in the cytoskeleton of epithelial cells, with a low or absent expression in the majority of normal adult epithelia while its upregulation has been observed in several types of cancers." (PMID 34737886, 2021). "In cancer cells, FSCN1 upregulation is associated with E-cadherin downregulation, decreased cell-cell adhesion, and increased migration, prompting us to investigate the role of GRHL3 in Fscn1 regulation in wound-front keratinocytes during reepithelialization." (PMID 34494554, 2021). "Furthermore, cytokines (IL-6 or tumor necrosis factor-alpha (TNF-α) trigger the NF-κB and STAT3 pathways, which are essential for enhancing FSCN1 expression in cancer." (PMID 34830909, 2021). "The oncogenic role of FSCN1 has been described in multiple cancers including ESCC." (PMID 34016787, 2021). "As an actin-bundling protein, FSCN1 plays an important role in cancer progression and metastasis." (PMID 33614909, 2021).
cancer (continued). "Is FSCN1 a promising cancer biomarker that can be used in clinical practice?" (PMID 33614909, 2021). "Additionally, FSCN1 also regulates oxidative phosphorylation of the mitochondria and metabolic stress resistance, thus inducing cancer metastasis." (PMID 34830909, 2021). "Evidence suggests that FSCN1 expression in cancer cells is involved in chemoresistance." (PMID 33614909, 2021). "There are multiple mechanisms for FSCN1 upregulation in human cancers." (PMID 33614909, 2021). "More studies are needed to determine whether FSCN1 has value as a biomarker in the most relevant cancers, over biomarkers that are in current clinical use, and whether targeting FSCN1 with small molecules will be useful for cancer therapy." (PMID 33614909, 2021). "FSCN1 has recently become a focus of research as a novel biomarker for many types of cancers." (PMID 33709519, 2021). "Silencing FSCN1 promotes apoptosis of cancer cells with PIK3CA alterations, thus enhancing radiosensitivity, and this process may be associated with the downregulation of YWHAZ." (PMID 34249689, 2021). "In multiple types of cancers, in vitro studies demonstrated that overexpression of miRNAs targeting FSCN1 in cancer cell lines reduce cell growth, proliferation, migration, and invasion, thus indicating miRNAs or miRNA-based reagents as potential therapeutic options." (PMID 34830909, 2021). "Studies have shown that FSCN1 is expressed in many human cancer types." (PMID 33614909, 2021). "Mechanisms of transcriptional regulation for FSCN1 in human cancers have been studied." (PMID 33614909, 2021). "FSCN1 was usually up-regulated in many malignant tumors and could be considered as an oncogene by promoting migration and invasion of tumors cells." (PMID 33753991, 2021). "FSCN1 is upregulated in several cancers and is over-expressed in AML compared to healthy controls." (PMID 34727888, 2021). "Furthermore, only a few relevant studies have been performed to investigate the potential of FSCN1 as a biomarker in certain types of human cancer." (PMID 33614909, 2021). "Silencing FSCN1 enhances radiosensitivity and promotes apoptosis in cancer cells with PIK3CA alterations, and this process may be associated with the downregulation of YWHAZ." (PMID 34249689, 2021). "It is shown that FSCN1 is an unusual biomarker and a potential therapeutic target for cancer." (PMID 33614909, 2021). "The observations in this study identify an important regulatory mechanism of fascin-1 in BLCA, and the TGF-β1/ZEB1-AS1/miR-200b/FSCN1 axis may serve as a potential target for cancer therapeutic purposes." (PMID 30823924, 2019). "Many scholars have studied the molecular mechanism of FSCN1 in many different cancers." (PMID 31043585, 2019). "FSCN1 is a newly identified miR-145 target in a few cancers." (PMID 28881818, 2017). "Also, recently, we found that miR-145 inhibits cell migration through the down-regulation of Fascin-1 (FSCN1), E-cadherin, β-catenin, and catenin δ-1 in various cancer cells." (PMID 26036261, 2015). "However, previous studies showed that FSCN1 is highly expressed in different cancer tissues or cells, such as cancers of as the mammary glands, colon, stomach, ovary, esophagus, and lung." (PMID 22292984, 2012). "Because both of these studies focused on analysis of the mouse fascin-1 promoter, it remains unclear whether FSCN1 could be a direct target of β-catenin/TCF transcriptional regulation in human carcinomas." (PMID 19340314, 2009). "Collectively, these data do not support the hypothesis that β-catenin has a specific role in regulating FSCN1 transcriptional activity in fascin-positive human carcinoma cells." (PMID 19340314, 2009). "On the basis of the comparative genomic analysis, we hypothesised that either or both of regions A and B might have significant regulatory roles in controlling FSCN1 transcription in human carcinoma cells." (PMID 19340314, 2009).
cancer (continued). "Furthermore, FSCN1 is a downstream target of several microRNAs and participates in various biological processes, such as epithelial-to-mesenchymal transition and autophagy, which regulate the invasion and migration ability of cells in various cancers." (PMID 35711849, 2022). "Furthermore, we discuss the clinical significance of FSCN1 in various cancers." (PMID 35711849, 2022). "In addition, FSCN1 is directly targeted by several miRNAs in different cancers." (PMID 34830909, 2021). "Furthermore, previous studies reported that FSCN1 could promote cancer progression by inducing chemoresistance in cancer cells as well as controlling metabolism and contributing to a de-differentiated and more stem-like state." (PMID 34830909, 2021). "However, overactive FSCN1 has been reported to be pro-tumorigenic in a variety of cancers." (PMID 34536950, 2021). "However, studies on the clinical significance of FSCN1 in human cancers are in the initial stages." (PMID 33614909, 2021). "In addition, FSCN1 regulates focal adhesion dynamics, cell migration and invasion, histone methylation and gene transcription, extracellular vesicle release, and cancer cell stemness, independently of its actin-bundling activity." (PMID 33614909, 2021). "Therefore, much remains to be learned about the role of FSCN1 in human cancers." (PMID 33614909, 2021). "Furthermore, FSCN1 overexpression enhances the metastasis of cancer cells." (PMID 33614909, 2021). "Indeed, through analysis of the activity of a set of promoter reporter constructs we have demonstrated a central importance of the FSCN1 promoter region −219/+114, (that contains conserved region A), in providing positive transcriptional regulation in human carcinoma cells." (PMID 19340314, 2009). "The widespread relevance of the FRA1 transcriptional network is evident across multiple aggressive cancer types, where FRA1 expression correlates with AXL, CDK6, and FSCN1 levels and poor patient outcomes." (PMID 41286309, 2025). "FSCN1 (rs852479, rs1640233) and HOTAIR (rs920778) were genotyped using TaqMan real-time PCR assay in 200 BC patients and 200 cancer-free controls, all representing Egyptian women." (PMID 38587571, 2024). "These genes are GAPDH, FSCN1, SLC2A1, FAM83A, PLEK2, and GJB3, some of which have been previously documented in various cancer types." (PMID 38370379, 2024). "FSCN1 is an actin binding protein, it promotes cell migration, adhesion, invasion through EMT process, and its expression reduces the chemosensitivity of cancer cells to paclitaxel." (PMID 37025163, 2023). "We further identified a DC subset with elevated expression of LAMP3, FSCN1, and CCR7 as migratory DCs (migDCs), as described recently in healthy thymus and various cancer types including breast." (PMID 36609566, 2023). "While FSCN1 and EMT-TF expression has been described in various cancers, there is little research on how they interact." (PMID 37832352, 2023). "Thus, FSCN1 may functions in the development of cancer via a variety of mechanisms." (PMID 35178306, 2022). "In lean NASH-HCC, methylation differences were seen in genes involved with cancer progression and prognosis (including HCC), such as CHCHD2, FSCN1, and ZDHHC12, and lipid metabolism, including PNPLA6 and LDLRAP1." (PMID 36474183, 2022). "Although in vitro studies using FSCN1-specific nanobodies in breast (MDA-MB-231) and prostate (PC3) cancer cells inhibited the formation of invadopodium and cell invasion, the use of FSCN1-specific antibodies in clinical settings needs to be established." (PMID 34830909, 2021). "Then we measured FSCN1 expression in human cancer tissues and adjacent non-carcinoma tissues (ANT) and explored the relationship between FSCN1 expression and clinical pathological factors and prognosis in TSCC patients." (PMID 31043585, 2019).
cancer (continued). "To further investigate FSCN1 expression in TSCC, we performed IHC analysis of 106 paraffin-embedded TSCC tissues, involving 95 tissues with both carcinoma tissues and the matched ANT tissues." (PMID 31043585, 2019). "FSCN1, a member of the FSCN family of actin-binding proteins, has an important role in cell proliferation, migration and invasion in various types of cancer and was identified as a predictable downstream target of miR-145." (PMID 28388536, 2017). "Direct regulation of some oncogenes involved in cancer cell invasion and metastasis, like MUC1, FSCN1, NEDD9 and SOX9, by miR-145 has been identified in many cancers 90–93." (PMID 25124875, 2014). "Although FSCN1 promotes the progression of many human cancers, it has not yet been approved as a biomarker in clinical practice." (PMID 37875732, 2023). "Through bioinformatics analysis, we found that FSCN1 could interact with IRF4, which is involved in the oncogenesis of multiple cancers." (PMID 37491232, 2023). "Through negative modulation of GSK3β, MYCT1, Fascin actin-bundling protein 1 (FSCN1), and TFF1, miR-632 modulated the WNT/β-catenin pathway and subsequently promoted cancer cell migration, invasion, proliferation, tube formation, and endothelial cell recruitment." (PMID 35242169, 2022). "In addition, expression of FSCN1 is higher in tongue squamous cell carcinoma (TSCC) tissues and cells than in adjacent non-carcinoma tissues and normal control cells." (PMID 35711849, 2022). "In this regard, it was found that FSCN1 can promote cancer progression through both canonical and non-canonical pathways by triggering cancer proliferation, migration, invasion, and metastasis." (PMID 34830909, 2021). "Even though FSCN1 is not a secreted or membrane-bound protein, serum levels of FSCN1 play a role in cancer diagnosis and prognosis." (PMID 33614909, 2021). "Second, because FSCN1 is not a secreted or membrane-bound protein, it cannot be used as a serum biomarker for different cancer types." (PMID 33614909, 2021). "Although mutations or amplification of FSCN1 gene are not common, hypomethylation of FSCN1 promoter has been found in normal epithelium and cancer cells alike, indicating the lack of epigenetic aberration of FSCN1 in cancer." (PMID 34830909, 2021). "Although FSCN1 promotes the progression of many human cancers, it is not currently listed as a cancer-driver gene." (PMID 33614909, 2021). "While in normal tissues there is low or lack of FSCN1 expression, in transformed epithelial cells and carcinomas, it is highly expressed." (PMID 34830909, 2021). "To analyze FSCN1 mRNA and protein expression in TSCC tissues (T) and the adjacent non-carcinoma tissues (ANT), we performed qRT-PCR assay and found that the expression of FSCN1 mRNA was demonstrably higher in T than in ANT in 48 pairs of fresh frozen tissues from TSCC patients (p < 0.0001)." (PMID 31043585, 2019). "Among them, we selected the actin-binding protein gene ANLN because our past studies showed that several actin-binding protein genes (CORO1C, FSCN1,LASP1 and MSN) were overexpressed in cancer tissues and were deeply involved in promoting human cancer cell migration and invasion." (PMID 28881803, 2017). "The function of FSCN1 and ID1 in promoting normal angiogenesis and cancer metastasis is well known." (PMID 26167915, 2015). "In contrast, in PCa bone metastasis, active OBs, osteocytes and fibroblast-like stromal cells surrounding areas of cancer cell growth are FSCN1-positive, while cancer cells are negative." (PMID 25485970, 2014). "It has not been established whether the expression of FSCN1 in human cancers is regulated by β-catenin-TCF signaling." (PMID 33614909, 2021). "However, the synthetic lethal interaction between FSCN1 and the PI3K–Akt pathway in cancer cells remains unknown." (PMID 34249689, 2021). "Also, CCAT1 could affect chemoresistance of cancer cells to paclitaxel (PTX) via regulating miR‐24‐3p and FSCN1 expression." (PMID 33709519, 2021).